RNU6-145P (RNA, U6 small nuclear 145, pseudogene)
Gene: Small nuclear RNA gene on chromosome 4 (76,532,222 to 76,532,327, reverse strand). Ensembl gene ENSG00000207307.
Homologues: Orthologues: chimpanzee U6 (98% identical), guinea pig U6 (94% identical), guinea pig U6 (93% identical), macaque U6 (88% identical), mouse Gm23186 (88% identical), pig U6 (86% identical), rat LOC120098049 (82% identical). Paralogues in human: RNU6-33P (95% identical), RNU6-1 (94% identical), RNU6-116P (94% identical), RNU6-2 (94% identical), RNU6-22P (94% identical), RNU6-3P (94% identical), RNU6-4P (94% identical), RNU6-5P (94% identical), RNU6-6P (94% identical), RNU6-9 (94% identical), RNU6-12P (93% identical), RNU6-13P (93% identical), and 1284 more.